NPIPA2 (nuclear pore complex interacting protein family member A2)
Synonyms: NPIP
Tractability: No criterion of Open Targets' tractability assessment is met for any kind of drug.
Gene: Protein-coding gene on chromosome 16 (14,742,533 to 14,765,462, forward strand). Ensembl gene ENSG00000254852.
Subcellular location (Human Protein Atlas): Nucleoplasm
Genetic constraint (gnomAD): Loss-of-function variants: 0 observed, 1.01 expected, observed/expected ratio (o/e) 0, 90% interval 0 to 1.72. That is too few expected variants to judge how well the gene tolerates losing a copy. Missense variants: 1 observed, 26.93 expected, observed/expected ratio (o/e) 0.0371, 90% interval 0.012 to 0.18. Synonymous variants: 1 observed, 9.65 expected, observed/expected ratio (o/e) 0.1, 90% interval 0.036 to 0.49.
Homologues: Paralogues in human: NPIPA3 (99% identical), NPIPA1 (89% identical), NPIPA6 (88% identical), NPIPA9 (88% identical), NPIPA7 (88% identical), NPIPA8 (88% identical), NPIPA5 (83% identical), NPIPB4 (75% identical), NPIPB5 (75% identical), NPIPB12 (75% identical), NPIPB13 (75% identical), NPIPB11 (74% identical), and 7 more.
Diseases named in the same sentence as NPIPA2 in open-access papers:
NPIPA2 is named in the same sentence as 2 diseases in open-access papers, as found by Europe PMC text mining. Sharing a sentence is not in itself a finding about the gene and the disease. The quoted sentences say what the papers report.
ovarian carcinoma (1 paper, 2020). A malignant neoplasm originating from the surface ovarian epithelium. "Based on whole-genome cDNA microarray analysis, KRASG12D/K104Q decreased expression of NPIPA2, DUSP1 and IL6 in lung and ovarian cancer cells." (PMID 33060649, 2020).
NPIPA2 also shares sentences with these, for which no sentence is quoted: cancer (1 paper).